TUBB3 (tubulin beta 3 class III)
Description:
Tubulin is the major constituent of microtubules, protein filaments consisting of alpha- and beta-tubulin heterodimers. Microtubules grow by the addition of GTP-tubulin dimers to the microtubule end, where a stabilizing cap forms. Below the cap, alpha-beta tubulin heterodimers are in GDP-bound state, owing to GTPase activity of alpha-tubulin. TUBB3 plays a critical role in proper axon guidance and maintenance. Binding of NTN1/Netrin-1 to its receptor UNC5C might cause dissociation of UNC5C from polymerized TUBB3 in microtubules and thereby lead to increased microtubule dynamics and axon repulsion. Plays a role in dorsal root ganglion axon projection towards the spinal cord.
Synonyms: TUBB4; beta-4; CFEOM3; CFEOM3A; CDCBM; CDCBM1; FEOM3
Tractability: Small molecule: an approved drug acts on it; a structure with a bound ligand is known; a high-quality ligand is known; it belongs to a druggable protein family. PROTAC: ubiquitination databases record sites on it; its protein half-life has been measured; a small molecule that binds it is known. Other modalities: an approved drug acts on it.
Target class: Structural protein
Chemical probes: PACLITAXEL (high quality)
Gene: Protein-coding gene on chromosome 16 (89,921,392 to 89,938,761, forward strand). Ensembl gene ENSG00000258947.
Subcellular location: Cytoplasm, cytoskeleton; Cell projection, growth cone; Cell projection, lamellipodium; Cell projection, filopodium
Subcellular location (Human Protein Atlas): Microtubules; Basal body; Cytokinetic bridge; End piece; Flagellar centriole; Mitotic spindle; Primary cilium; Primary cilium tip; Principal piece
Pathways (Reactome):
Cell Cycle: EML4 and NUDC in mitotic spindle formation; Mitotic Prometaphase; Recruitment of NuMA to mitotic centrosomes; Resolution of Sister Chromatid Cohesion; Sealing of the nuclear envelope (NE) by ESCRT-III; Separation of Sister Chromatids; The role of GTSE1 in G2/M progression after G2 checkpoint
Vesicle-mediated transport: COPI-dependent Golgi-to-ER retrograde traffic; COPI-independent Golgi-to-ER retrograde traffic; COPI-mediated anterograde transport; Gap junction assembly; Microtubule-dependent trafficking of connexons from Golgi to the plasma membrane; Translocation of SLC2A4 (GLUT4) to the plasma membrane
Metabolism of proteins: Carboxyterminal post-translational modifications of tubulin; Formation of tubulin folding intermediates by CCT/TriC; Post-chaperonin tubulin folding pathway; Prefoldin mediated transfer of substrate to CCT/TriC
Signal Transduction: Hedgehog 'off' state; RHO GTPases Activate Formins; RHO GTPases activate IQGAPs
Immune System: MHC class II antigen presentation; PKR-mediated signaling
Neuronal System: Activation of AMPK downstream of NMDARs; Assembly and cell surface presentation of NMDA receptors
Organelle biogenesis and maintenance: Cargo trafficking to the periciliary membrane; Intraflagellar transport
Autophagy: Aggrephagy
Cellular responses to stimuli: HSP90 chaperone cycle for steroid hormone receptors (SHR) in the presence of ligand
Developmental Biology: Recycling pathway of L1
Disease: HCMV Early Events
Hemostasis: Kinesins
Gene Ontology:
Molecular function: GTP binding; netrin receptor binding; protein binding; structural constituent of cytoskeleton; GTPase activity; peptide binding
Biological process: axon guidance; dorsal root ganglion development; microtubule cytoskeleton organization; mitotic cell cycle; microtubule-based process; netrin-activated signaling pathway; neuron differentiation
Cellular component: ciliary tip; cilium; extracellular exosome; intercellular bridge; microtubule; microtubule cytoskeleton; mitotic spindle; nucleus; sperm end piece; sperm principal piece; axon; dendrite; filopodium; growth cone; lamellipodium; cell periphery; cytoplasm; cytoskeleton; neuronal cell body
Genetic constraint (gnomAD): Loss-of-function variants: 17 observed, 36.93 expected, observed/expected ratio (o/e) 0.46, 90% interval 0.31 to 0.69. The upper end of that interval is the gene's LOEUF score, 0.69, which puts it in group 2 of 6, group 1 being the genes least tolerant of losing a copy. Missense variants: 262 observed, 661.56 expected, observed/expected ratio (o/e) 0.4, 90% interval 0.36 to 0.44. Synonymous variants: 332 observed, 282.97 expected, observed/expected ratio (o/e) 1.17, 90% interval 1.07 to 1.28.
Gene-disease validity (ClinGen):
ClinGen rates the evidence that TUBB3 causes each of these diseases.
TUBB3-related tubulinopathy (autosomal dominant): Definitive. A tubulinopathy syndrome associated with malformations of cortical development, axon guidance defects, white matter abnormalities, and/or congenital fibrosis of the extraocular muscles (CFEOM), due to de novo or dominantly inherited variants with high penetrance.
Homologues: Orthologues: dog TUBB3 (100% identical), macaque TUBB3 (100% identical), mouse Tubb3 (99% identical), rat Tubb3 (99% identical), tropical clawed frog tubb3 (99% identical), chimpanzee TUBB3 (97% identical), guinea pig TUBB3 (97% identical), rabbit TUBB3 (96% identical), pig TUBB3 (75% identical). Paralogues in human: TUBB4B (92% identical), TUBB6 (92% identical), TUBB (91% identical), TUBB2B (91% identical), TUBB4A (91% identical), TUBB2A (91% identical), TUBB8 (86% identical), TUBB8B (84% identical), TUBB1 (78% identical), TUBA1B (43% identical), TUBA1A (43% identical), TUBA4A (42% identical), and 11 more.
Diseases named in the same sentence as TUBB3 in open-access papers:
TUBB3 is named in the same sentence as 159 diseases in open-access papers, as found by Europe PMC text mining. Sharing a sentence is not in itself a finding about the gene and the disease. The quoted sentences say what the papers report.
ovarian carcinoma (30 papers, 2007 to 2023). A malignant neoplasm originating from the surface ovarian epithelium. "In ovarian cancer specimens, high levels of TUBB3 mRNA and βIII-tubulin protein were significantly associated with increasing levels of SOX9 and HIF2α." (PMID 35573698, 2022). "Epigenetic study of 66 primary ovarian tumors and 3 ovarian cancer cell lines has revealed that DNA methylation and chromatin acetylation are partly associated with TUBB3 overexpression in ovarian cancer." (PMID 24551595, 2014). "This study assessed the role of miR-200c as regulator of class III β-tubulin (TUBB3), a factor associated with drug-resistance and poor prognosis in ovarian cancer." (PMID 23394580, 2013). "Because TUBB3 is among the factors associated with drug-resistance in ovarian cancer, we set out to investigate the correlation between TUBB3 expression and expression of miR-200c in the same panel of cell lines." (PMID 23394580, 2013). "Many preclinical studies have shown high expression levels of TUBB3 are associated with paclitaxel resistance in human lung cancer, ovarian cancer, prostate cancer and breast cancer cell lines." (PMID 21586171, 2011). "In A2780 ovarian cancer cells, hypoxia has been shown to strongly induce TUBB3 gene and βIII-tubulin protein expression and this phenotype was directly linked to cisplatin and paclitaxel resistance." (PMID 35573698, 2022). "For example, in ovarian cancer cells, DNA demethylation CpG island (containing 86 CpGs) within TUBB3 intron 1 has been shown to result in βIII-tubulin overexpression, with chromatin acetylation accelerating the process and increasing TUBB3 expression as well." (PMID 35573698, 2022). "For example, overexpression of Semaphorin-6A (SEMA6A) is correlated with TUBB3/βIII-tubulin upregulation in ovarian cancer cells, while the reverse is observed in SEMA6A knockdown cells." (PMID 35573698, 2022). "While both appear to have a positive impact on expression in ovarian cancer, HIF1α appears to play an inhibitory role on TUBB3/βIII-tubulin expression in glioblastoma cells." (PMID 35573698, 2022). "Further, loss of miR-200c led to the induction of Snail and ZEB1, activation of EMT, and abnormal expression of beta-tubulin III (TUBB3), leading to paclitaxel resistance in ovarian cancer cell models." (PMID 32266287, 2020). "The combined presence of high TUBB3/SOXn levels is associated with a relevant reduction of PFS and overall survival in women with ovarian cancer." (PMID 31057614, 2019). "Restoration of miR-200c expression in an intraperitoneal xenograft model of human ovarian cancer reduced TUBB3 expression and resulted in a significantly decreased tumor burden." (PMID 28587302, 2017). "Re-expression of miRNAs of the miR-200 family reduced expression of its target genes, including ZEB1, ZEB2, FN1 and class III β-tubulin (TUBB3), and inhibited ovarian cancer cell migration and invasion." (PMID 28399108, 2017). "One of the mechanisms that contributes to chemotherapy resistance in ovarian cancer is through TUBB3, a class III β-Tubulin." (PMID 27601996, 2016). "This is in direct contrast to the previous findings and prompted the researchers to propose a model that describes the two different mechanisms by which miR-200c regulates TUBB3 mRNA in ovarian cancer." (PMID 26213923, 2015). "Alteration in the expression of class III β-Tubulin (TUBB3) is one of the mechanisms by which ovarian cancer cells gain resistance to microtubule-targeting agents." (PMID 26213923, 2015). "Posttranscriptional inhibition of TUBB3 gene expression has been reported for miR-200c in Hey ovarian cancer cells and in HeC50 endometrial cancer cells." (PMID 23394580, 2013). "Nanofluidic technology and immunohistochemistry were used to analyze the expression of HuR, TUBB3 and miR-200c in 220 ovarian cancer patients." (PMID 23394580, 2013).
ovarian carcinoma (continued). "A good outcome, better than average, can be predicted for those patients who exhibit ovarian cancer with nuclear HuR pattern, high levels of miR-200c, and low levels of TUBB3." (PMID 23394580, 2013). "This study suggests a model for the combined regulatory activity of miR-200c and HuR on TUBB3 expression in ovarian cancer." (PMID 23394580, 2013). "In summary, the results of our study revealed that HuR plays a pivotal role in driving TUBB3 expression and the aggressive phenotype in ovarian cancer, through its interaction with miR-200c." (PMID 23394580, 2013). "We conclude that only the combined assessment of miR-200c, HuR, and TUBB3 is useful for tailoring specific protocols aimed at differentiating appropriate treatment modalities in ovarian cancer." (PMID 23394580, 2013). "In studies of lung cancer, breast cancer and ovarian cancer, there are reverse relations between TUBB3 expression and paclitaxel efficacy or prognosis of patients." (PMID 21586171, 2011). "Likewise, levels of the transcription factor ZEB1 have also been shown to influence TUBB3 expression in ovarian cancer in the same manner as Semaphorin-6A." (PMID 35573698, 2022). "The expression of all five members of this miRNA family have been shown to inversely correlate with the levels of TUBB3 in ovarian cancer patients, however only two of them, miR-200b and −200c, have been demonstrated to directly bind to TUBB3, while miR-429 is predicted to do so." (PMID 35573698, 2022). "Upregulation of TUBB3 expression can destabilize microtubules and inhibit taxanes, which has been confirmed in various types of cancer, including breast cancer, lung cancer, ovarian cancer, prostate cancer, stomach cancer, and pancreatic cancer." (PMID 35204496, 2022). "In addition to its function in diabetes, miR-200c facilitates the regulation of the expression of class III beta-tubulin (TUBB3) under the hypoglycemic condition in ovarian cancer." (PMID 32938376, 2020). "The EMT phenotype of ovarian cancer cells along with TUBB3, tubulin polymer, and apoptotic genes may serve as biomarkers for responsiveness to taxanes, and modification of these markers should be considered as therapeutic targets in cancers." (PMID 28399108, 2017). "These differential associations between TUBB3, ELAVL1, and miR-200c may clarify the differences in the chemotherapy treatment outcomes particularly in the action of miR-200c in ovarian cancer." (PMID 27601996, 2016). "Moreover, the prognostic roles of miR-200c and TUBB3 in restoring chemotherapy sensitivity in ovarian cancer is possibly a cell-context dependent." (PMID 27601996, 2016). "Since the expression of TUBB3 is required for chemoresistance to microtubule-binding agents (e.g., taxanes and vinca alkaloids), restoration of miR-200c down-regulates TUBB3, and effectively re-sensitizes ovarian cancer cells to paclitaxel." (PMID 24782983, 2014). "Also in other studies about breast cancer, ovary cancer, head and neck neoplasms, there were relationship between TUBB3 expression and response or survival of paclitaxel." (PMID 21586171, 2011). "Additionally, epigenetic regulation could account for this regulation in specific cancer cell lines, as hypomethylation of the HRE is required for TUBB3 expression in ovarian cancer cells, prostate cancer cells and prostate tumours." (PMID 35573698, 2022). "The altered expression level of TUBB3 was observed in many human cancer cells, and its aberrant expression was found to be associated with enhanced chemoresistance and poor prognosis in NSCLC, ovarian cancer, gastric cancer, breast cancer, and uterine serous carcinoma." (PMID 34094924, 2021). "The overexpression of miR-200c led to suppression of TUBB3 and restored the paclitaxel sensitivity in chemotherapy-resistant cancer cell lines and in a xenograft tumor model, suggesting the positive role of miR-200-c as therapeutic agents in ovarian cancer treatment." (PMID 27601996, 2016).
ovarian carcinoma (continued). "For example, high expression of tubulin beta 3 class III (TUBB3) and low expression of salt inducible kinase (SIK2), polo-like kinase 2 (PLK2) or spleen tyrosine kinase (SYK) restore the paclitaxel sensitivity of ovarian cancer cells." (PMID 35477477, 2022). "Clinical relevance of SOX9 in ovarian cancer relies on its coexpression with HIF-2α under hypoxia conditions, promoting TUBB3 expression." (PMID 31057614, 2019). "One study in an ovarian cancer cell line revealed that hypoxia, via hypoxia-inducible factor-1a (HIF-1a), is able to induce TUBB3 expression." (PMID 24396456, 2014). "One of the validated targets of the miR-200 family is TUBB3 (class III β-tubulin), whose overexpression has been reported in several malignancies, including ovarian cancer." (PMID 23394580, 2013). "We have previously reported that both paclitaxel and cisplatin, standard chemotherapies used for the treatment of ovarian cancer patients, promotes an increase in the expression of the chemoresistant markers ERCC1 and TUBB3 and the CSC markers CD44, CD133, OCT4A and EpCAM in ovarian cancer cells." (PMID 33023532, 2020). "It shows that TUBB3 expression does not correlate with tumor recurrence after taxane treatment in ovarian cancer as well as hGBP-1 expression does.But it also leaves some questions unanswered." (PMID 28090373, 2016). "When ovarian tumors of all histologies, grades, and stages were segregated into those with low and high TUBB3 expression, the differences in TUBB3 expression in ovarian cancers were not correlated with changes in PFS." (PMID 28090373, 2016). "TUBB3 has been shown to be highly expressed in a variety of types of cancer, including NSCLC, breast cancer, ovarian cancer, head and neck cancers and cancers of unknown primary site." (PMID 24396456, 2014). "In ovarian cancer cells, HuR enhanced tubulin beta III (TUBB3) in conjunction with miR-200c." (PMID 23965981, 2013).
breast carcinoma (27 papers, 2011 to 2025). "The possible association of TUBB3 overexpression with cancer aggressiveness or metastasis has been reported for several cancers, including non-small-cell lung cancer, breast cancer, urinary bladder cancer, and esophageal adenocarcinoma." (PMID 30034996, 2018). "Interestingly, according to several clinical trials, a high level of TUBB3 is associated with negativity for estrogen and progesterone receptors in breast cancer patients and, as a result, with worse disease-free and overall survival." (PMID 37065867, 2023). "A previous study in breast carcinoma reported that TUBB3 messenger RNA expression was associated with reduced survival, although the authors did not identify a significant association when TUBB3 expression was determined by TUBB3 IHC analysis." (PMID 29383151, 2017). "In vitro analysis of 23 colorectal cancer cell lines suggested that TUBB3/βIII-tubulin is activated after exposure to androgens in males, as seen with estrogens in breast cancer cells." (PMID 35573698, 2022). "Downregulation of TUBB3 was closely correlated with inhibited breast cancer cell proliferation and promoted cell apoptosis." (PMID 35173149, 2022). "In concert with our findings, a previous study found that the mRNA levels of TUBB3 had correlation with lymph nodes status, tumor stages, and molecular markers of breast cancer." (PMID 35173149, 2022). "The ability of MZF1 to bind to the TUBB3 loci was identified while looking for means to upregulate βIII-tubulin expression in HER2 positive breast cancer in an effort to induce sensitivity to the TBA, vinorelbine." (PMID 35573698, 2022). "(G) Western blot of MEX3A and TUBB3 in SOX11+ breast cancer cell lines and SOX11- DCIS.com and MCF10A from the MCF10A mammary cell progression series." (PMID 32909943, 2020). "As with SOX11, both distant metastasis-free survival and overall survival of breast cancer patients are reduced when high levels of TUBB3, an established SOX11 target in neural cells, are expressed in primary tumours." (PMID 32909943, 2020). "(H) Pie charts representing the percentage of breast cancer samples with a log2 fold-change greater than two in the levels of MEX3A or TUBB3 RNA when SOX11 increased between 0.5- and 2-fold, 2- and 4-fold, or greater than 4-fold in the TCGA dataset." (PMID 32909943, 2020). "We found many SOX11+ breast cancer cell lines express high levels of MEX3A or TUBB3 compared to DCIS.com cell line." (PMID 32909943, 2020). "This was further substantiated by selective depletion of TUBB3 in a series of breast cancer cell lines expressing high levels of TUBB3." (PMID 29069726, 2017). "Pre-clinical studies have suggested that underexpression of TUBB3 predicts sensitivity to taxanes whereas overexpression predicts resistance in breast cancer, NSCLC and gastric cancers." (PMID 27888622, 2017). "Lastly, we set out to examine the functional relevance of TUBB3 overexpression in taxol resistance in a panel of breast cancer cell lines." (PMID 29069726, 2017). "In a level ID breast cancer study, patients overexpressing TUBB3 had a higher probability of response to docetaxel but the predictive effect of TUBB3 underexpression was not assessable." (PMID 27888622, 2017). "Low mRNA and protein expression of MAPT was correlated with high expression of TUBB3, which showed prognostic significance with disease-free survival and overall survival in patients with early breast cancer." (PMID 24369726, 2013). "Several clinical studies have assessed the prognostic or predictive value of TUBB3 expression in patients with ovarian, cervical, or breast cancer." (PMID 24053422, 2013). "Overall, our experimental methods and the creation of a breast cancer plasticity model validated the TUBB3-GFP knock-in reporter strategy as an effective tool for investigating the connection between nerves and cancer and could be applied in vitro or in vivo." (PMID 37046688, 2023).